ESR1 (estrogen receptor 1)
Diseases named in the same sentence as ESR1 in open-access papers (continued):
Sharing a sentence is not in itself a finding about the gene and the disease.
breast tumors (continued). "For example, in studies of breast tumors it may be important to determine the expression level of the genes ESR1 and ERBB2, which correspond to the clinically important estrogen receptor (ER) and Her2 proteins." (PMID 22172014, 2011). "Tumor gene expression profiles (NKI-147) were processed in the same fashion as the sorted cell lines and tumor profiles were compared to the ESR1, GATA3, and c-Myb gene signatures to demonstrate which breast tumor subtypes were enriched for these signatures (left)." (PMID 20949095, 2010). "Levels of ESR1 and ERBB2 gene expression were inversely correlated in these samples (r = -0.57, P = 0.0005, Pearson correlation), as has been shown in many other studies of breast tumours." (PMID 17555561, 2007). "Whether ERβ can bind ESR1 regulatory regions and cross-regulate its expression in normal tissue, in which it is expressed to higher levels than in breast tumors, remains to be clarified." (PMID 34831189, 2021). "Although there are discordant results described in the literature, for example the deletion of the CYP2D6 gene in breast tumor tissue is reported to cause departures from HWE23, it seems unlikely that the ESR1 gene is deleted in our study as HWE is not violated." (PMID 33547330, 2021). "The authors showed that mutant ESR1 tumors are highly dependent on HSP90, and preclinical studies with the HSP90 inhibitor STA9090 demonstrated cytotoxicity alone and in combination with raloxifene and fulvestrant to ex vivo cultured circulating breast tumor cells." (PMID 26059247, 2015). "AFF4 mRNA is highly expressed in luminal A, luminal B, and some Her2-positive tumors, but is absent in the basal subtype of breast tumors, suggesting that the expression of AFF4 and ESR1 has a positive correlation." (PMID 32265480, 2020). "Similar results were obtained by Tramm and colleagues who showed that the surrounding non-neoplastic tissue does not affect the quantification of ESR1, PGR, and ERBB2 mRNA expression in breast tumor samples." (PMID 25218890, 2014). "The ESR1 gene is shared among 3 pathways: "PELP1 Modulation of Estrogen Receptor Activity pathway", "CARM1 and Regulation of the Estrogen Receptor pathway", and "Downregulated of MTA 3 in ER negative Breast Tumors pathway"." (PMID 18254968, 2008). "In an independent series of breast tumor samples (19 nonrelapsing and 14 relapsing), reduced expression of ESR1/ERα, IGFBP4, SNCG, BCL2, and FOS was observed in the relapsing group and was associated with a shorter overall survival." (PMID 18928543, 2008). "Our analysis of breast tumor transcriptome datasets, however, revealed that in tumors with lower PGR expression, the clinical PR status does not correlate accurately with the expression of ESR1 or of ER target genes, including PGR itself." (PMID 36358871, 2022).
endometrial cancer (362 papers, 2007 to 2026). Primary or metastatic malignant neoplasm involving the endometrium (mucous membrane that lines the endometrial cavity). "ESR1, which encodes an estrogen receptor implicated in the development of endometrial cancer, has been linked to recurrent miscarriages." (PMID 40336816, 2025). "It is known that gynecological cancers, such as ovarian cancer and low-grade endometrial cancer, are often characterized by the expression of the estrogen receptor ERα, encoded by ESR1." (PMID 40429755, 2025). "For endometrial cancer, ESR1 expression has been associated with lower grade and stage of the cancer." (PMID 38582811, 2024). "But the importance of ESR1 mutation in endometrial carcinoma treated by endocrine therapy is not fully understood." (PMID 37924026, 2023). "The aim of this study was to explore the incidence and clinical relevance of circulating ESR1 mutations in patients treated by AI or megestrol acetate (M) for advanced endometrial carcinoma." (PMID 37924026, 2023). "The aim of this study was to explore the incidence and clinical relevance of circulating ESR1 mutations in patients treated by AI or M for advanced endometrial carcinoma." (PMID 37924026, 2023). "Since SYNE1 is located 19 kb downstream of ESR1 (the ERα gene), its association with estrogen action in ovarian cancer, endometrial cancer, and endometriosis has been reported." (PMID 35976950, 2022). "To date, the detection of ESR1 mutations has been reported in cervical squamous cell carcinoma and in a patient with endometrial cancer treated with an aromatase inhibitor." (PMID 35954453, 2022). "It has also been reported that the presence of ESR1 mutations is associated with worse outcomes in endometrial cancer." (PMID 35954453, 2022). "ESR1 encodes an estrogen receptor, plays a crucial role in the occurrence and progression of breast and endometrial cancer, and is the main reason for resistance to estrogen suppression therapy." (PMID 36437939, 2022). "Apart from endometrial cancer studies, there are very few studies that show the existence of ESR1 mutations in ovarian cancer." (PMID 35954453, 2022). "ESR1 encodes a transcription factor that activates estrogen receptors and ligands, and is considered to be a driving event for breast and endometrial cancer." (PMID 34381020, 2021). "Very recently, a de Novo ESR1 Hotspot Mutation was detected in a patient with endometrial cancer treated with an aromatase inhibitor, while it has been reported that—in endometrial cancer—ESR1 mutations are associated with worse outcomes and less obesity." (PMID 33535614, 2021). "We identified the expected strong association of co-expression between PGR and ESR1 (q-value < 2.42 × 10− 53 and odds ratio = 182), which is consistent with previous findings from endometrial cancer cohorts." (PMID 32894083, 2020). "Oestrogen receptor α (ESR1) has great impact on the susceptibility and prognosis of endometrial cancer." (PMID 30640723, 2019). "A role for E2 in inhibiting EMT in humans was suggested in a study which found that reduced expression of ESR1 was associated with increased expression of genes involved in EMT in endometrial carcinoma samples." (PMID 30165855, 2018). "Splice variants of ESR1 that alter the hormone-binding domain have been associated with ERα activation by Tamoxifen in endometrial cancer cells." (PMID 27160768, 2016). "Most of the studies support the mechanism in which ESR1 gene mutations promote the development and progression of endometrial cancer by altering estrogen metabolism." (PMID 23593326, 2013). "Meta-analysis of the associations between ESR1 PvuII and XbaI polymorphisms and endometrial cancer risk." (PMID 23593326, 2013).
endometrial cancer (continued). "The aim of this meta-analysis is to derive a more precise estimation of the associations between eight polymorphisms in the ESR1 gene and endometrial cancer risk." (PMID 23593326, 2013). "The ESR1 gene encoding the estrogen receptor 1 is a newly identified oncogene for endometrial cancer." (PMID 23593326, 2013). "In spite of these limitations, however, our present meta-analysis includes the largest number of eligible studies relevant to the relationship between ESR1 polymorphisms and endometrial cancer risk reported to date." (PMID 23593326, 2013). "These relationships will promise us a functional profiling of ESR1 gene and an understanding of the biological processes associated with endometrial cancer development and progression." (PMID 23593326, 2013). "This recent meta-analysis is aimed to update previous meta-analysis, as well as to provide a more comprehensive and reliable conclusion on the associations between eight common functional polymorphisms in the ESR1 gene and endometrial cancer susceptibility." (PMID 23593326, 2013). "Another useful example is the association between receptor estrogen alpha (ESR1) gene GVs and endometrial cancer." (PMID 21286314, 2010). "ESR1 is the main estrogen receptor expressed in the endometrium and has been proposed to play a pivotal role in determining endometroid endometrial carcinoma risk, the most common histological subtype among endometrial malignancies." (PMID 21286314, 2010). "Neither the single tagSNP analysis nor the window analysis showed an association of common genetic variation in the ESR1 gene with myometrial invasion or endometrial cancer survival." (PMID 19319135, 2009). "Most earlier genetic association studies of the ESR1 gene in relation to endometrial cancer risk have focused on only a few common genetic polymorphisms." (PMID 19319135, 2009). "We found five adjacent tagSNPs covering a region of 15 kb at the 5′ end of ESR1 that decreased the endometrial cancer risk." (PMID 19319135, 2009). "The common variation in the EGF gene has never before been investigated with regard to endometrial cancer susceptibility, but a few studies have been published regarding ESR1 and endometrial cancer risk." (PMID 19319135, 2009). "In conclusion, we found an association between genetic variation in ESR1 and endometrial cancer risk; the rs9340799 GG genotype was associated to an almost 50 percent decreased risk for endometrial cancer compared to the AA genotype." (PMID 18990228, 2008). "The receptor encoded by the ESR1 gene plays a pivotal role in breast and endometrial cancer." (PMID 41516250, 2025). "ERα, encoded by the ESR1 gene, belongs to the steroid hormone receptor superfamily and is essential for mediating estrogen-induced proliferation in hormone-responsive cancers, such as endometrial cancer." (PMID 40521202, 2025). "ESR1, mainly encoding the estrogen receptor, is closely associated with breast and endometrial cancers; many studies have reported that the estrogen receptor plays a crucial anti-GC role by arresting the cell cycle and inducing apoptosis, invasion, and migration." (PMID 37361599, 2023). "First, the sample size is still relatively small and may not provide sufficient statistical power to estimate the correlations between ESR1 gene polymorphisms and endometrial cancer risk." (PMID 23593326, 2013). "Genetic and epigenetic changes in ESR1 gene may lead to differences in estrogen metabolism and thereby possibly explain inter-individual differences in endometrial cancer risk." (PMID 23593326, 2013). "Emerging evidence indicates that common functional polymorphisms in the estrogen receptor 1 (ESR1) gene may have an impact on an individual’s susceptibility to endometrial cancer, but individually published results are inconclusive." (PMID 23593326, 2013). "However, further studies are still needed in order to validate the associations between polymorphisms in ESR1 and endometrial cancer." (PMID 23593326, 2013).
endometrial cancer (continued). "However, they failed to assess the relationship between the other common polymorphisms in the ESR1 gene and endometrial cancer risk." (PMID 23593326, 2013). "However, the previous meta-analysis did not provide convincing and reliable evidences in associating ESR1 polymorphisms to endometrial cancer risk because it presented some obvious shortcomings." (PMID 23593326, 2013). "Variation in this gene is particularly interesting because estrogen receptors have been implicated in disease processes in breast cancer, endometrial cancer, and osteoporosis and the ESR1 SNP rs2228480 was previously found to show association with breast cancer." (PMID 24403849, 2013). "The gene coding for the ESR1 protein could thus play a role in susceptibility and prognosis of endometrial cancer." (PMID 19319135, 2009). "We found that intronic variation in ESR1 was associated with endometrial cancer risk." (PMID 18990228, 2008). "We show that non-coding variation in ESR1 is associated with endometrial cancer risk." (PMID 18990228, 2008). "We have investigated whether polymorphic variation in the ESR1 is associated with invasive endometrial cancer risk, overall and in subgroups defined by other hormonally related factors." (PMID 18990228, 2008). "We have investigated whether polymorphic variation in the estrogen receptor alpha gene (ESR1) is associated with endometrial cancer risk." (PMID 18990228, 2008). "Therefore, it was hypothesized that polymorphisms in the ESR1 gene could be functional and were associated with endometrial cancer risk." (PMID 23593326, 2013). "However, a 5′ region of five tagSNPs in ESR1 decreased endometrial cancer risk in our dataset." (PMID 19319135, 2009). "In this study, we enriched tumour stem cells from endometrial cancer cells and observed the relationship between the expression of ESR1 and the malignant behaviour of tumour stem cells induced by oestrogens." (PMID 40342082, 2025). "For example, endometrial cancer is characterized by intrachromosomal amplification of ESR1, KRAS, PIK3CA, ERBB2, TERC, MYC, CCNE1." (PMID 41415205, 2025). "ESR1 silencing has also been observed in other cancers, including endometrial cancer, where ESR1 promoter methylation led to decreased ERα expression." (PMID 39796024, 2024). "The ESR1 gene refers to estrogen receptor signaling, which is involved in the progression of breast and endometrial cancers in female subjects." (PMID 35626739, 2022). "A recent study showed that PGR and ESR1 peaks in Ishikawa endometrial cancer cells are mostly in the A (active) compartment (79% and 83%, respectively)." (PMID 35681455, 2022). "The exposure of human endometrial cancer cells to 17β-estradiol promoted p62 phosphorylation and increased ESR1 protein expression." (PMID 34575683, 2021). "Estrogen receptor 1 (ESR1) gene plays an active role in the progression of various cancers such as breast, prostate, and endometrial cancer." (PMID 33742334, 2021). "Oestrogen receptors α and β encoded by ESR1 and ESR2, respectively, have been extensively studied due to the assumed role of oestrogens in the development of endometrial cancer." (PMID 32066633, 2020). "In the present study, loss of NR4A1 expression co-occurs with existing endometrial cancer subtypes, as we observed a positive relationship between NR4A1 and ESR1 expression." (PMID 32894083, 2020). "In the context of endometrial cancer, receptLoss correctly identified several well-known nuclear hormone receptors, including ESR1, AR, and PGR, that have previously been shown to have low expression in a subset of endometrial carcinomas." (PMID 32894083, 2020). "The amplification of ESR1 was described in mastopathic breast tissue, which progressed to invasive cancer or pre-malignant endometrial cancers, implying early ESR1 amplification and its role in carcinogenesis." (PMID 30995757, 2019).
endometrial cancer (continued). "For example, the expression of KLF9 was shown to be inversely correlated with endometrial tumor grade, and its silencing was further proposed to contribute to the etiology of endometrial cancer initiated by aberrant ESR1 signaling." (PMID 31821171, 2019). "It is well-established that endometrial cancer type I is estrogen-dependent, ESR1-positive, and is the most common form of endometrial cancer (>80% of the endometrial cancer cases)." (PMID 28827707, 2017). "As a result, in the Results section under subheading ‘Hormone-binding domain truncated ESR1 amplifications in primary endometrial cancers’." (PMID 28664899, 2017). "To mimic more advanced endometrial cancer which is associated with loss of ERα and PR, we applied CRISPR-Cas9 technology to delete ERα at the genomic level (ESR1) in the ERα- and PR-positive ECC1 endometrial cancer cells using three different sgRNA sequences." (PMID 26859414, 2016). "Here, we demonstrate for the first time that nucleophosmin (NPM1/B23) suppression can restore the expression of estrogen receptor α (ESR1/ERα) in endometrial cancer cells." (PMID 27527851, 2016). "Across a cancer study subset of 29 primary endometrial carcinomas that had gone on to metastasize, we characterized the copy-number changes by GeneChips and validated amplifications of ESR1 in these cancers by fluorescence in-situ hybridization (FISH)." (PMID 27160768, 2016). "Thus, genetic mutations in ESR1 gene may contribute to its abnormal expression and are probably linked to increased risk of hormone-related cancers such as the breast, prostate, and endometrial cancers." (PMID 23593326, 2013). "ESR1 is the principal ER expressed in the endometrium and is thought to be important in the development of endometrial carcinoma." (PMID 23624782, 2013). "The Hec50 and AN3CA cell lines represent aggressive type 2 endometrial cancers that have lost epithelial markers including E-cadherin and ESR1 and gained mesenchymal markers such as N-cadherin and vimentin, indicative of EMT." (PMID 21501518, 2011). "We intended to study common variation in both the ESR1 (MIM 133430) and EGF (MIM 131530) genes in relation to endometrial cancer risk, myometrial invasion and endometrial cancer survival." (PMID 19319135, 2009). "In the current study, we went on to explore the gene in greater detail and found a 5′ region of five tagSNPs in the ESR1 gene – including the PvuII (TAG6, rs2234693) and XbaI (TAG7, rs9340799) variants – that decreased endometrial cancer risk." (PMID 19319135, 2009). "We investigated common genetic variation in the entire ESR1 and EGF genes in relation to endometrial cancer risk, myometrial invasion and endometrial cancer survival." (PMID 19319135, 2009). "In 702 cases with invasive endometrial cancer and 1563 controls, we genotyped five markers in ESR1 and used logistic regression models to estimate odds ratios (OR) and 95 percent confidence intervals (CI)." (PMID 18990228, 2008). "Our study is population-based and the largest investigating the relation between ESR1 and endometrial cancer to date." (PMID 18990228, 2008).